HMGB1 (high mobility group box 1)
Diseases named in the same sentence as HMGB1 in open-access papers (continued):
Sharing a sentence is not in itself a finding about the gene and the disease.
Stroke (continued). "The HMGB1 released during a stroke may function as one of the factors that provoke the contraction of microvessels." (PMID 33321691, 2020). "In particular, HMGB1 expression was found in the serum samples of stroke patients." (PMID 33384585, 2020). "Besides participating in endogenous EPC-mediated neurovascular remodeling during stroke recovery, HMGB1 also involves in exogenous EPC-mediated stroke recovery." (PMID 33384585, 2020). "Because HMGB1 impaired the reuptake and clearance of glutamate in astrocytes in response to ischemic injury, we suggest that glycyrrhizic acid can antagonize the impaired function and possibly act as a promising adjuvant therapy for stroke in the future." (PMID 33287126, 2020). "HMGB1 works as a DAMP that exacerbates acute brain injury after a stroke." (PMID 33384585, 2020). "Some studies have explored the alterations of HMGB1 in adult stroke." (PMID 33384585, 2020). "HMGB1 can induce excitatory neurotransmitter release in the brain after stroke." (PMID 31001089, 2019). "HMGB-1 functions also as a proinflammatory factor, promotes cell toxicity and cell death, regulates clot-promoting properties which propagate further inflammation and coagulation, and contributes to the initiation and progression of stroke." (PMID 31708728, 2019). "Therefore, HMGB1 participates in the destruction of the BBB after stroke and leads to inflammation in brain tissue." (PMID 31001089, 2019). "During cellular stress such as stroke, HMGB1 functions as a proinflammatory cytokine." (PMID 31291966, 2019). "Thus, HMGB1 released from ischemic brain mediates post-stroke angiogenesis at the advanced stage, subsequently promoting brain repair and disease recovery." (PMID 31001089, 2019). "While our data do not support the hypothesis that HMGB-1 is involved in maintaining immunosuppression, additional studies are required to further define the role of HMGB-1 in stroke induced immunosuppression." (PMID 31118917, 2019). "However, following a stroke, HMGB1 is translocated to the cytosol and secreted into the extracellular space." (PMID 31001089, 2019). "HMGB1 levels are enhanced in patients with strokes, acute myocardial infraction, and arthritis." (PMID 30539006, 2018). "Authors concluded that post-stroke bone fracture enhances macrophage infiltration via an HMGB1-dependent mechanism, and that HMGB1 may be a promising target in minimizing the adverse consequences of bone fracture following stroke." (PMID 29786644, 2018). "This study aimed to investigate the change of HMGB1 after thrombolytic therapy and whether blocking HMGB1 could ameliorate the neurovasculature complications secondary to tPA treatment in stroke rats." (PMID 30139371, 2018). "Other mechanism which could be responsible for post-stroke immunodepression is a release of high mobility group box 1 (HMGB1) from the necrotic brain tissue to blood." (PMID 29669581, 2018). "Interestingly, while HMGB1 levels in penumbra increased depending on stroke severity, they decreased in infarct cores due to an acute and massive neuronal cell death in cortices of the ipsilateral hemisphere." (PMID 29555931, 2018). "In particular, we and others have reported that in a rat middle cerebral artery occlusion (MCAO) stroke model, massive release of HMGB1 is promoted by N-methyl-d-aspartic-induced acute neuronal death, exacerbating neuronal damage and triggering delayed inflammatory processes." (PMID 29555931, 2018). "HMGB1 may also provide a novel link for brain-immune communication leading to post-stroke immunomodulation." (PMID 29054968, 2017). "However, the inhibitory effects of EE on post-stroke anxiety (PSA)-like behavior were attenuated by the treatment with HMGB1 inhibitor glycyrrhizin (P<0.05)." (PMID 28845299, 2017).
Stroke (continued). "In neuroinflammation following TBI and stroke or in neurodegeneration, the damaged neural cell becomes oxidized and disulfide (S-S) bridges are formed between Cys23 and Cys45 while Cys106 can remain -SH; in this situation HMGB1 is proinflammatory." (PMID 28890893, 2017). "Furthermore, HMGB1 and RAGE play a role in the progression of DM, which is one of the risk factors for stroke." (PMID 29054968, 2017). "Moreover, mechanisms for hyperglycemia-induced exacerbation of the stroke pathophysiology including excitotoxicity and HMGB1 cascades have been already well established." (PMID 28152042, 2017). "Therefore, HMGB1 is new promising therapeutic intervention aimed at promoting neurovascular repair and remodeling after stroke." (PMID 29054968, 2017). "HMGB1-mediated effect on angiogenesis may present a possible target for augmenting recovery several days after stroke onset." (PMID 29054968, 2017). "We further demonstrated that IL-6 promoted angiogenesis in enriched animals after ischemic stroke, indicating that the promoting effects of astrocytic HMGB1 in the post-stroke angiogenesis and functional recovery were mediated by the secretion of IL-6 from astrocytes." (PMID 28845299, 2017). "No statistical associations were observed between the HMGB1 rs2249825 variant and the stroke subtypes in the healthy controls." (PMID 29245967, 2017). "Of note, experimental evidences indicate that HMGB1 may participate in further excitotoxicity in the penumbra after stroke by stimulating NMDA receptors and the release of excitatory amino acids." (PMID 28152042, 2017). "In vivo evidence demonstrated that genetic ablation of RAGE reduced the infarct volume and abrogated macrophage activation in mice and that the knockdown of HMGB1 expression by intra-striatal infection of HMGB1-shRNA reduced infarct size and microglia activation in experimental stroke models." (PMID 29245967, 2017). "In patients with stroke, HMGB1 levels are adequately associated with IL-6 levels but not with the magnitude of brain tissue damage as evaluated by CT morphometry." (PMID 29054968, 2017). "In stroke and brain injury, HMGB-1 might be released from ischemic neurons, brain microglia, and activated monocytes/macrophages, potentially mediating deleterious inflammatory responses." (PMID 26115623, 2016). "HMGB1 mediated activation of RAGE leads to microglia recruitment in a model of stroke." (PMID 26921471, 2016). "This idea is even more clinically relevant in light of a recent study showing that serum HMGB1 levels may be a valuable prognostic marker in stroke patients." (PMID 27544687, 2016). "We speculated that T cell activity is directly related to HMGB1 release after stroke and that Gly inhibited T cell activity via inhibition of HMGB1 release." (PMID 27609334, 2016). "We further hypothesized that T cell activity is modulated by HMGB1, and that Gly inhibits T cell activity via inhibition of HMGB1 release after stroke, based on the following reasons." (PMID 27609334, 2016). "In stroke patients, serum HMGB1 levels positively correlate with stroke severity." (PMID 27544687, 2016). "The confocal microscopy results suggest a strong immunostaining of HMGB1 in the nuclei of neurons in sham animals, but its expression was robustly reduced after stroke, suggesting that HMGB1 might have been released." (PMID 27609334, 2016). "Taken together, inhibition of HMGB1 release and T cell function may be a major reason for the protective effects of Gly against stroke." (PMID 27609334, 2016). "We then further examined whether Gly administration inhibited HMGB1 release after stroke and whether HMGB1 promoted T cell activity." (PMID 27609334, 2016). "The increase of HMGB1 expression in diabetic stroke mice had a detrimental effect, as expected." (PMID 27596007, 2016). "To prove this, we first examined HMGB1 expression in the ischemic brain 3 days after stroke." (PMID 27609334, 2016).
Stroke (continued). "Taken together, Gly administration inhibited HMGB1 release from the ischemic brain after stroke." (PMID 27609334, 2016). "First, HMGB1 is released in the brain from necrotic neurons as early as 1 h after stroke and is released into the cerebral spinal fluid (CSF) and bloodstream after stroke." (PMID 27609334, 2016). "In mice and men a stroke-size dependent up-regulation of high-motility group protein 1 (HMGB1) could be shown, although it has to be taken into account that signals differ in the subacute and the chronic phases after stroke induction." (PMID 25898363, 2015). "Our recent work showed that plasma levels of HMGB1 increased after the onset of IS, and inhibition of HMGB1 activity via administration of a recombinant-soluble form of receptor for advanced glycation end-products significantly improved outcome in a mouse stroke model." (PMID 24912490, 2014). "It has been reported that reactive astrocytes expressing HMGB1 in the peri-infarct cortex may promote neurovascular remodeling and functional recovery after stroke, suggesting that these cells may in fact also possess beneficial effects." (PMID 24970310, 2014). "For example, in animal models of stroke, HMGB1 is released rapidly before pronounced cell death and treatment with neutralizing HMGB1 antibodies or HMGB1 inhibitor glycyrrhizin reduces ischemia-induced neuroimmune gene induction and brain damage as well as spinal cord damage." (PMID 24551070, 2014). "In patients who are currently taking the ARBs telmisartan, irbesartan, and candesartan, it is unclear whether the effect of inhibition of the HMGB1/RAGE axis directly contributes to stroke therapy." (PMID 24065095, 2013). "Indeed, our data showed that splenectomy reduced HMGB1 release in the plasma, which suggests a correlation between the reduction in HMGB1 release and attenuation in lymphopenia after splenectomy in stroke." (PMID 23555048, 2013). "Evidence is rapidly accumulating to suggest that HMGB1 may play an important role in brain injury following stroke." (PMID 22883976, 2012). "Indeed, in a small series of stroke patients serum HMGB1 was elevated as demonstrated in western blots." (PMID 20090932, 2010). "HMGB1 is therefore a candidate molecule that could serve as possible mediator of T cell activation in stroke." (PMID 20090932, 2010). "The aim of the present study was to examine the association between changes in serum levels of HMGB1 following acute ICH and stroke severity and investigate the underlying mechanism, in an attempt to shed light on the role of HMGB1 in ICH-caused inflammatory injury." (PMID 20936104, 2010). "In summary, the interplay of HMGB1 release, inflammatory response, and neutrophil extracellular trap generation may be critical for stroke onset and progression, and HMGB1 may serve as a novel target for anti-inflammation and thrombosis, especially in patients with neocoronary stroke." (PMID 38740617, 2025). "However, HMGB1 may exert a significant role in promoting vascular remodeling and neurological recovery during the acute (4–5 days to 1 week after stroke) and subacute(1–3 weeks after stroke), and chronic (> 3 weeks after stroke) phases." (PMID 38740617, 2025). "MALAT1/miR-181c-5p/HMGB1 axis may be a key pathway of antiinflammation induced by berberine, highlighting its potential as a therapeutic targets for modulating inflammation and improving stroke outcomes." (PMID 39859155, 2025). "Furthermore, heightened levels of HMGB1 have been implicated in the development of cognitive deficits in preclinical studies utilizing animal models of ischemic brain injury, while HMGB1 inhibition resulted in improved memory and learning post-stroke in rodents." (PMID 38708343, 2024).
Stroke (continued). "Elucidating the specific mechanisms by which HMGB1 signaling triggers subacute and long-term neuroinflammation that may lead to post-stroke cognitive deficits is an important avenue for the development of targeted therapies to improve functional outcomes after ischemic brain injury." (PMID 38708343, 2024). "In addition, HMGB1 seems to play different roles in different stroke subtypes, and whether these differences are related to the redox modification of HMGB1 remains unknown." (PMID 37062906, 2023). "HMGB1 expression has been investigated in Alzheimer’s disease, amyotrophic lateral sclerosis, Huntington’s disease, Parkinson’s disease, multiple sclerosis, neuromyelitis optica, neuropathic pain, epilepsy, stroke, intracerebral hemorrhage, and traumatic brain injury." (PMID 36232519, 2022). "In the early stage after stroke, the activation of danger-associated molecular patterns (DAMP) causes the damaged brain to secrete various antigens such as ATP, high mobility group protein 1 (HMGB1), heat shock protein (HSP) and nicotinamide adenine dinucleotide (NAD)." (PMID 35720359, 2022). "Therefore, it is necessary to carefully consider whether to promote or inhibit HMGB1 in different stages of stroke." (PMID 34372857, 2021). "Indeed, TLR4 mediated action in astrocytes may contribute to HMGB1 action on the brain in experimental rat stroke models." (PMID 34208101, 2021). "Therefore, Sirt1 activation after a stroke may be a strategy to prevent subsequent neurodegeneration by inhibition of both neuronal and endothelial amyloidogenic pathways as well as HMGB1-mediated neuroinflammation." (PMID 33318474, 2020). "In addition, the HMGB1-mediated angiogenesis effect may be a viable target for enhancing recovery several days after stroke onset." (PMID 33384585, 2020). "Therefore, Sirt1-dependent endothelial HMGB1 secretion in patients following a stroke might be a target to prevent progression to AD, although further in vivo and clinical studies are needed to confirm this." (PMID 33318474, 2020). "Therefore, Sirt1-mediated inhibition of HMGB1 release, or neutralization of HMGB1 from endothelial cells might be a target for the prevention of post-stroke neurodegeneration." (PMID 33318474, 2020). "Moreover, another important role of HMGB1 after stroke is to promote endothelial cell sprouting." (PMID 31001089, 2019). "Given that HMGB1 has been reported to deteriorate neurovascular complications in stroke and might be elevated after tPA treatment evidenced in our present study, preventing HMGB1 signaling might provide a good strategy to attenuate the side effects caused by tPA." (PMID 30139371, 2018). "The rapid early changes observed in experimental stroke models could be prevented by blocking β-adrenoceptors with propranolol or by neutralizing HMGB-1 activity with antibodies or an antagonist of its receptor, the receptor for advanced glycation end-products (RAGE)." (PMID 28331857, 2017). "Therefore, it remains unknown how the timing of catecholamine and HMGB-1 actions affects the development of stroke-induced immune alterations." (PMID 28331857, 2017). "Additionally, HMGB1 plays a biphasic role in inflammation and stroke." (PMID 29245967, 2017). "Furthermore, direct links also exist between thrombin and HMGB1: HMGB1 is involved in a number of systemic vascular diseases and is also increased in stroke, while both HMGB1 and thrombin are released in various neurologic conditions and HMGB1 promotes coagulation." (PMID 28890893, 2017). "In addition to suggesting a potential mechanism for hypothermia’s therapeutic effects, our results suggest HMGB1 modulation may lengthen the therapeutic window for stroke treatments." (PMID 27544687, 2016). "However, the extracellular release of HMGB1 appears to be common to the etiology and progression of multiple diseases leading to stroke, and may act in a multi-stage process in stroke." (PMID 24065095, 2013).
Stroke (continued). "Therefore, the HMGB1/RAGE axis could be considered as a candidate molecular target for the treatment of stroke." (PMID 24065095, 2013). "Inhibition of the HMGB1/RAGE axis may prove to be a novel therapeutic strategy for treating stroke." (PMID 24065095, 2013). "Also, in sera of stroke patients HMGB1 concentrations were increased (p = 0.0002)." (PMID 20090932, 2010). "As a decoy strategy, sRAGE can compete with RAGE to block the HMGB1/RAGE signaling pathway and has been shown to attenuate ischemic damage in stroke." (PMID 40406124, 2025). "This study investigated the role of High mobility group box 1 (HMGB1), a prototype DAMP molecule, in NETosis induction following photothrombotic stroke (PTS), with a particular focus on neutrophil-platelet interactions." (PMID 39910417, 2025). "Atorvastatin significantly attenuated ischemia-induced overexpression of HMGB1, RAGE, TLR4, and NF-κB, significantly improving neurological deficits and reducing cerebral edema and infarct size 24 h after stroke." (PMID 38740617, 2025). "In our study, an increased expression of HMGB1, TLR4 and NF-κβ1 was observed in the subacute phase, one week after the onset of stroke." (PMID 40332314, 2025). "A chronic high-fat diet was found to exacerbate pyroptosis and necroptosis and worsen ischemic brain pathology by enhancing the HMGB1/TLR4/NF-κB signaling pathway after cerebral ischemia–reperfusion injury and leading to poor outcomes after stroke." (PMID 38740617, 2025). "In this study, we explored the relationship between HMGB1/TLR4/RAGE and the effect of BCP in vivo and in vitro to provide a theoretical basis for the application of BCP in stroke." (PMID 40128654, 2025). "Platelet depletion or platelet-specific knockdown of HMGB1 significantly reduced plasma HMGB1 and NET levels after stroke and greatly improved stroke prognosis." (PMID 38740617, 2025). "HMGB1 levels positively correlated with markers of neural damage like S100B and NSE in stroke patients." (PMID 38708343, 2024). "While our study focused on the relationship between HMGB1 and PSCI, it is important to consider the potential interactions of HMGB1 with broader neuroinflammatory processes in the context of stroke and cognitive impairment." (PMID 38708343, 2024). "HMGB-1 produced in stroke-injured tissue can enter circulation through the BBB with increased permeability, thereby initiating post-stroke systemic inflammatory response syndrome." (PMID 36777635, 2023). "Researchers have discovered that the High Mobility Group Box 1 (HMGB1) protein plays a key role in the regulation of iron levels in the brain, which can contribute to the severity of stroke damage." (PMID 37907744, 2023). "Platelet-derived high-mobility group box-1 (HMGB1) is a major inducer of NET production in ischemic stroke, and HMGB1-depleted attenuates NET formation after stroke and betters neurologic outcomes." (PMID 36873885, 2023). "HMGB1 has been implicated in a variety of inflammatory conditions including sepsis, inflammatory bowel disease, pancreatitis, acute lung injury, rheumatoid arthritis, hemorrhagic shock lacking infection, traumatic brain injury, stroke, depression, and ischemia-reperfusion injury." (PMID 35573828, 2022). "Depletion of platelets or platelet-specific knockout of HMGB1 significantly reduced plasma HMGB1 and NET levels after stroke, and greatly improved stroke outcomes." (PMID 35358095, 2022). "Using this model, we observed a significant increase in circulating levels of HMGB1 and MPO-DNA complexes 6 and 24 hours after stroke in comparison with sham animals, consistent with our observations in human ischemic stroke patients." (PMID 35358095, 2022). "Platelet-specific HMGB1 knockout reduces platelet-induced NET formation and improves stroke outcomes." (PMID 35358095, 2022).